MUC5AC (mucin 5AC, oligomeric mucus/gel-forming)
Diseases named in the same sentence as MUC5AC in open-access papers (continued):
Sharing a sentence is not in itself a finding about the gene and the disease.
polyp (10 papers, 2006 to 2023). A usually exophytic mass attached to the underlying tissue by a broad base or a thin stalk. "By using DNA microarray analysis, we identified 46 upregulated related genes, including MUC5AC (6.25 fold) and act1 (4 fold), in nasal epithelial cells, confirming the association of IL-17A, MUC5AC and act1 in polyp tissues." (PMID 24892823, 2014). "Presence of dysplasia didn't cause any difference in MUC5AC Ab positivity in sera and MUC5AC expression in polyp specimens." (PMID 16409634, 2006). "Having MUC5AC expression at polyp specimens cause antibody formation against MUC5AC antigen at patients sera in the same time period." (PMID 16409634, 2006). "There was significant association of IL-17A and MUC5AC mRNA in polyp tissues (p<0.05)." (PMID 24892823, 2014). "The increased act1 production was shown to be significantly associated with IL-17A levels in polyp tissues, providing a clue that the IL-17A/act1 axis may play a crucial role in MUC5AC production in NP patients." (PMID 24892823, 2014). "We next examined the gene expression levels of IL-17A, MUC5AC and act1 in polyp tissues and normal controls." (PMID 24892823, 2014). "In accordance with the histological staining, the mRNA levels of IL-17A and MUC5AC were significantly increased in polyp tissues compared with the normal controls (p<0.05)." (PMID 24892823, 2014). "We found that increased IL-17A production was significantly correlated with MUC5AC and act1 expression and goblet cell hyperplasia in polyp tissues (p<0.05)." (PMID 24892823, 2014). "Further immunohistochemical studies indicated that gastric foveolar metaplasia is associated with surface epithelium covering upper two thirds of the polyp, showing immunohistochemical positivity for mucin 5 AC (MUC5AC)." (PMID 24422755, 2014). "Both IL-17A and MUC5AC immunostaining were significantly increased in polyp tissues compared with the normal controls (p<0.05)." (PMID 24892823, 2014). "Immunohistochemically, positivity of MUC5AC staining decreased in the lower one third of the polyp, particularly on the distal side." (PMID 24422755, 2014). "We enrolled 25 NP patients and 22 normal controls and examined the expression of IL-17A, MUC5AC and act1 in polyp tissues by immunohistochemical (IHC) staining, quantitative polymerase chain reaction (qPCR) and western blot." (PMID 24892823, 2014). "In polyp patients, the presence of serum MUC5AC antibody correlates with the expression of MUC5AC antigen in the patients polyp specimen." (PMID 16409634, 2006). "MUC5AC serum antibody levels in healthy controls, in polyp and malignant colorectal carcinoma patients." (PMID 16409634, 2006). "Serum MUC5AC antibody levels (OD unit) and MUC5AC expression in pathology specimens of polyp patients." (PMID 16409634, 2006). "Patients with villous adenoma didn't have MUC5AC Ab in sera and MUC5AC expression in polyp specimen." (PMID 16409634, 2006). "The presence of circulating free MUC5AC antibody levels was significantly correlated with expression of MUC5AC in polyp sections." (PMID 16409634, 2006). "We compared the presence of MUC5AC antibody with the expression of MUC5AC in the resected polyp tissue." (PMID 16409634, 2006). "The aim of the current study was therefore to investigate the effect of EGF on mucin MUC5AC expression and define the involvement of PI3K and TMEM16A in mediating the EGF-induced MUC5AC expression in primary nasal epithelial cell cultures derived from polyp tissue of CRSwNP patients." (PMID 32514271, 2020). "Considering the high clinical utility of the appropriate polyp classification, in this study, we evaluated the potential of colonic mucins (MUC1, MUC4, MUC17, MUC2, MUC5AC, and MUC6) and associated glycans (Tn/STn-MUC1 and CA19-9) for differentiating SSA/P from HP and TA." (PMID 27705923, 2017).
polyp (continued). "Several studies have previously reported MUC5AC expression in normal colon, HP, SSA/P, TSA, TA, VA, TVA and mixed polyps without emphasizing on its diagnostic utility for discriminating these polyp subtypes." (PMID 27705923, 2017). "Patients were faced firstly with MUC5AC Ag at polyp tissues." (PMID 16409634, 2006). "In the present study, MUC5AC expression was found in 46.5% of polyp specimens." (PMID 16409634, 2006). "Serum MUC5AC antibody correlated well with the presence of MUC5AC expression in polyp specimens." (PMID 16409634, 2006). "Immunohistochemical analysis was completed to demonstrate MUC5AC expression in the polyp specimens." (PMID 16409634, 2006). "In this study, we established a close relationship between excessive MUC5AC expression, goblet cell hyperplasia and IL-17A production in polyp tissues, providing the clue that Th17 cells may play an important role in the excessive MUC5AC production and goblet cell hyperplasia." (PMID 24892823, 2014). "We did, however, observe an overrepresentation of mucus secretory (goblet) cells with high expression of both MUC5AC and MUC5B in polyp epithelium, consistent with the mucus metaplasia observed in patients with CRSwNP." (PMID 35608904, 2022). "The expression of MUC1, MUC5AC, Tn/STn-MUC1, and CA19-9 were significantly increased in all types of polyp lesions (p < 0.0005) compared to adjacent normal colon (NC)." (PMID 27705923, 2017). "However, when we attempted to evaluate the importance of IL-13 in MUC5AC production and glandular hyperplasia, we only observed very low levels of IL-13 in these polyp tissues and we failed to establish association between IL-13 and MUC5AC expression in this cohort (data not shown)." (PMID 24892823, 2014). "The mean number of IL-17A+ cells per HPF was 6.7[2.9, 11.8] in polyp tissues and 1.6[0.8, 2.4] in normal controls; the mean staining score of MUC5AC was 2.2[1.7, 3.0] in polyp tissues and 0.6[0.4, 1.1] in normal controls." (PMID 24892823, 2014). "The mRNA level of IL-17A was 3.3[2.0, 5.5] in polyp tissues and 0.8[0.4, 1.2] in normal controls, and the mRNA level of MUC5AC was 4.4[2.3, 6.3] in polyp tissues and 1.2[0.4, 2.2] in normal controls." (PMID 24892823, 2014). "Positive coefficients for MUC5AC in ordinal regression analysis indicate that increase of MUC5AC expression level does not increase the likelihood of a polyp to be of villous adenoma configuration." (PMID 20929551, 2010). "Among antibody negative patients in group I, 80% had negative MUC5AC expression in their polyp specimen." (PMID 16409634, 2006). "A total of 454 polyp specimens comprising 36 hyperplastic polyps, 15 serrated adenomas, 258 tubular adenomas, 114 tubulovillous adenomas, and 31 villous adenomas were included in this study, and were immunostained for MUC1, MUC2, MUC5AC and MUC6 by using mucin specific antibodies." (PMID 20929551, 2010).
Sjögren syndrome (10 papers, 2009 to 2020). "The levels of Muc5AC decreases in patients with Sjögren syndrome or other types of DED because of the abrogation of the function of the goblet cell." (PMID 31487776, 2019). "Levels of the gel-forming mucin Muc5AC decrease in patients with Sjögren syndrome and with other types of dry eye24,25, as well as in several dry eye animal models." (PMID 30002412, 2018). "Gel-forming mucin MUC5AC and MUC19 decline in Sjögren’s syndrome and other types of dry eye, MUC5AC was also suppressed in several dry eye animal models." (PMID 24498087, 2014). "This has been demonstrated most consistently with the findings of reduced secreted MUC5AC in the tears of Sjogren’s syndrome patients, and in their conjunctival cells compared to normals." (PMID 20806091, 2010). "Patients with Sjögren syndrome have reduced levels of the gel-forming mucin, MUC5AC, in tears, which correlates with a reduced number of MUC5AC transcripts in conjunctival goblet cells and is responsible for decreasing the fluid on wet epithelial surfaces." (PMID 19158956, 2009). "Interestingly, previous studies have reported that patients with Sjögren's syndrome have decreased MUC5AC in tears and in MUC5AC mRNA expression compared with control subjects." (PMID 33232357, 2020). "Besides, the level of MUC5AC as secreted mucins in tear fluid has been found to be reduced in individuals with Sjogren’s syndrome." (PMID 26048396, 2015).
gastric adenocarcinoma (9 papers, 2014 to 2025). "Meanwhile, when a GEN-FGML lesion is continuously accompanied with the common type of gastric adenocarcinoma consisting of differentiation toward gastric foveolar epithelium (MUC5AC-positive), it is also diagnosed as GA-FGM." (PMID 34268625, 2021). "Sox2 is a primary regulator of gastric differentiation that maintains gastric mucosal features and regulates the expression of gastric mucus genes, such as Muc5ac, and it is downregulated during the development of gastric adenocarcinoma." (PMID 26839577, 2016). "A subtype of GA-FG, gastric adenocarcinoma of fundic-gland mucosa type (GA-FGM), has also been proposed, which differs from GA-FG by being positive for MUC5AC." (PMID 40576943, 2025). "Immunohistochemical staining of CD10, MUC2, MUC5AC, and MUC6 was performed in 257 tissue samples from patients with early differentiated gastric adenocarcinomas." (PMID 34256780, 2021). "MUC5AC and MUC6 expression decreases during esophageal adenocarcinoma formation, but not gastric adenocarcinoma progression." (PMID 36994101, 2023). "Immunohistochemistry revealed that the tumor cells were positive for MUC5AC, but negative for MUC2 and MUC6, leading to a final diagnosis of foveolar-type gastric adenocarcinoma." (PMID 37663228, 2023).
influenza infection (9 papers, 2014 to 2023). "Influenza is known to induce the production of mucins in the respiratory tract as part of the host defense response, and increasing MUC5AC production is protective and improves viral clearance during influenza infection." (PMID 36999019, 2023). "Aerosolized nicotine also reduced BAL MUC5AC concentration and increased lung protein permeability induced by influenza infection." (PMID 36999019, 2023). "In this study, we have identified that nicotine in e-cigarette aerosols blunts the increase in the BAL concentration of mucin protein MUC5AC induced by influenza infection." (PMID 36999019, 2023). "Influenza infection increased BAL MUC5AC, but the increase was significantly less in mice exposed to aerosolized nicotine than in mice exposed to the carrier VG/PG or to air." (PMID 36999019, 2023). "Influenza infection significantly increased (p < 0.05) MUC5AC in the BAL at 7 dpi but to a lesser degree in mice exposed to VG/PG/Nic aerosol which had significantly lower BAL MUC5AC than mice exposed to the aerosolized carrier VG/PG or to air." (PMID 36999019, 2023). "A mouse model overexpressing Muc5ac in the lungs demonstrated protection against influenza infection via the trapping of viruses through the terminal sialic acids cloaking the mucin protein core." (PMID 36142171, 2022). "Compared to the aerosolized carrier VG/PG, in mice exposed to aerosolized nicotine there was a significantly lower amount of Mucin 5 subtype AC (MUC5AC) in the distal airspaces and significantly higher lung permeability to protein and viral load in lungs at 7 dpi with influenza." (PMID 36999019, 2023). "Given this protective role, the reduced BAL MUC5AC concentration following influenza infection may partially explain the impaired viral clearance in the mice that were exposed to aerosolized nicotine." (PMID 36999019, 2023). "In murine models of influenza infection, overexpression of the major respiratory tract gel-forming mucin, Muc5ac (non-human form of MUC5AC), revealed that this glycoprotein presents SAα2-3Gal, which can bind virus and limit infection of the underlying epithelia." (PMID 30761095, 2019). "Additionally, antiviral genes were also activated during the infection process with the exception of MUC5AC, which concurs with our previous finding where influenza does not alter MUC5AC expression." (PMID 30487780, 2018). "Indeed, it was clearly shown that the mere transgenic expression of Muc5ac, without the involvement of (IL-13-driven) inflammatory responses, is protective in influenza infections." (PMID 25398130, 2014).
lymph node metastasis (9 papers, 2014 to 2025). "While MUC1 expression is ubiquitous, MUC5AC expression has emerged as a significant prognostic factor associated with lymph node metastasis and poor OS." (PMID 38893239, 2024). "Lymph node metastasis has been identified as a prognostic factor in AoV cancer, and our study revealed an association between MUC5AC and lymph node metastasis." (PMID 38893239, 2024). "Additionally, decreased AQP-1 was associated with lymph node metastasis and increased MUC5AC was associated with decreased survival." (PMID 36672382, 2023). "Additionally, serum MUC5AC ≥ 14 ng/mL was associated with lymph-node metastasis, tumour stage (IVb) and a worse prognosis in BTC patients who underwent surgery, compared with patients with lower levels of this mucin." (PMID 30875782, 2019). "Additionally, serum MUC5AC ≥ 14 ng/mL was associated with lymph-node metastasis, tumour stage (IVb) and a worse prognosis in BTC patients who underwent surgery, compared to patients with lower levels of this mucin." (PMID 30875782, 2019). "The reduced levels of MUC5AC were linked to more aggressive features of the tumor, including TNM staging, histological classification, and lymph node metastasis." (PMID 40124374, 2025). "Our findings suggest the potential of MUC5AC as a biomarker for lymph node metastasis and the prognosis of AoV cancer." (PMID 38893239, 2024). "Although MUC1 expression is universal, MUC5AC expression is a significant prognostic indicator that correlates with lymph node metastasis and poor OS." (PMID 38893239, 2024). "The results showed that MUC5AC was significant for lymph node metastasis and was furthermore valuable as a prognostic factor for predicting overall survival." (PMID 38893239, 2024). "In subsequent multivariate analysis with curability as the covariate, lymph node metastasis, venous invasion, and MUC5AC and/or MUC16 expression were significantly related to the prognosis." (PMID 24722639, 2014). "Despite these findings, our study did not reveal significant associations between MUC1 or MUC5AC expression and histopathological features such as lymph node metastasis, LVI, PNI, TILs, or necrosis." (PMID 40821195, 2025). "Among six analyses using mature MUC5AC antibodies, associations were also found between increased MUC5AC and more advanced TNM staging (three studies), larger tumor size (one study), and increased frequency of lymph node metastasis (one study)." (PMID 36672382, 2023). "MUC5AC is a mucin, a secretory glycoprotein whose expression is characteristic of mucinous and endometrioid ovarian tumors, and its presence is associated with a lack of lymph node metastasis and a more favorable prognosis." (PMID 41373846, 2025).
cyst (8 papers, 2011 to 2025). A sac-like closed membranous structure that may be empty or contain fluid or amorphous material. "The O-linked glycomes of acidic glycoproteins from cyst fluids were found to be similar to oligosaccharide structures from a previously defined O-glycome of gastric mucins MUC5AC and MUC6, which were isolated from gastric tissues of healthy humans." (PMID 26075384, 2015). "MUC5AC expression in serum, pancreatic juice, and cyst fluid might help screen high-risk individuals for PDA, like young type 2 diabetes mellitus patients and patients with chronic pancreatitis." (PMID 34205412, 2021). "DEST analysis for EV in these matched samples demonstrated low plasma and cyst fluid expression for the malignant biomarkers Das-1, MUC5AC, and MUC6." (PMID 37414831, 2023). "In our study, the ovarian tumors, which showed a high level of expression of blood group antigens in cyst fluid glycoproteins, also revealed a strong reactivity towards the MUC5AC antibody." (PMID 26075384, 2015). "We used antibody-lectin sandwich assays to detect glycoforms of MUC5AC and endorepellin in cyst fluid samples from three independent cohorts of 49, 32, and 66 patients, and we used monoclonal antibodies to test for terminal, alpha-linked GlcNAc and the enzyme that produces it." (PMID 27992432, 2016). "The tissue staining of MUC5AC and the fucose binding lectin staining were found to coincide in the mucinous ovarian tumor tissue indicating that the two molecules were secreted by the same cell and suggested that blood group antigens could be carried by MUC5AC in the tissue and in cyst fluid." (PMID 26075384, 2015). "Although our data does not exclude the presence of other mucins in cyst fluids, it can be suggested that MUC5AC is the most abundant mucin-type glycoprotein in mucinous cyst fluids." (PMID 26075384, 2015).
ulcerative colitis (8 papers, 2008 to 2025). An inflammatory bowel disease involving the mucosal surface of the large intestine and rectum. "Although MUC5AC is expressed at low levels in the gastrointestinal tract and upregulated in pathological conditions such as ulcerative colitis or parasitic infection, under physiological conditions colonic goblet cells secrete MUC2." (PMID 30272559, 2018). "MUC5AC is also expressed at low levels in the gastrointestinal tract and, surprisingly, expressed de novo, and upregulated in colonic mucus from cancer and ulcerative colitis patients." (PMID 23741618, 2013). "With regard to the relationship between ulcerative colitis and ectopic MUC5AC expression in the mucous cells of the large intestines, patients with UC had levels above the threshold, and their mucosae were strongly labeled with anti-M1/MUC5AC antibody by immunohistochemistry." (PMID 24829572, 2014). "Human cancer cells and cells from patients with ulcerative colitis express and secrete MUC5AC." (PMID 23741618, 2013). "Muc5ac is a mucin, a type of glycoprotein normally expressed in non-intestinal mucosa, known to be involved in the inflammatory processes of diseases such as ulcerative colitis and adenocarcinoma." (PMID 40979361, 2025).
biliary tract cancer (7 papers, 2008 to 2023). "The diagnostic sensitivity of MUC4 in bile is 27%, and although the sensitivity of combined serum MUC5AC in the diagnosis of biliary tract cancer can be increased to 58%, it is still too low to be used as a diagnostic biomarker for biliary tract cancer." (PMID 36010914, 2022). "Mucin 5AC (MUC5AC) is rarely expressed in normal biliary epithelium, but is upregulated in biliary tract cancers and its enhanced synthesis is associated with unfavourable outcomes." (PMID 37628976, 2023). "MUC5AC is a serum candidate biomarker for the diagnosis of biliary tract cancer, and MUC4 is also an independent factor for the evaluation of iCCA and eCCA." (PMID 36010914, 2022).
bronchiectasis (7 papers, 2016 to 2024). Segmental, irreversible dilation of the bronchial tree resulting in the accumulation of secretions which leads to obstruction. "Mucins described in bronchiectasis (MUC2) may reflect bacterial load and P. aeruginosa colonisation and bronchiectasis severity as measured by the BSI (MUC2 and MUC5AC), suggesting a potential future role in incorporating these by-products in characterising phenotypes." (PMID 27941638, 2016).